LARS2 (leucyl-tRNA synthetase 2, mitochondrial)
Diseases named in the same sentence as LARS2 in open-access papers (continued):
Sharing a sentence is not in itself a finding about the gene and the disease.
tumor (12 papers, 2017 to 2026). "In contrast, the ‘tumor cells 2’ cluster was characterized by genes associated with protein synthesis (Cmss1, Rpph1, Rps12, Lars2, Ncl2), tumorigenesis (Mt-Rnr2, Hmga2, Mab1b) and cell–cell communication (Gphn, Camk1d, Il31ra, Cmss1, Rpph1), which may be indicative of an inflammatory phenotype." (PMID 39769061, 2024). "The downregulation of LARS2 enhances the proliferation of both types of cancer cells, which is a phenotype consistent with its role as a tumor suppressor, although how it impacts tumor development requires further investigation." (PMID 34361072, 2021). "CACNA2D2 gene, a subunit of the voltage-dependent calcium channel complex, is located in the 3p21.3 chromosomal region, a known tumor suppressor gene cluster, that also includes LARS2." (PMID 28460460, 2017). "Studies have shown that LARS2 is highly expressed in LARS B cells, mediating the immune escape of COAD cells and promoting tumor progression." (PMID 40230854, 2025). "The analysis of LARS2, SEZ6L2, and SOX7 in the COAD tumor microenvironment suggests that these genes play significant roles in regulating CD8+ T cell infiltration and function." (PMID 40230854, 2025). "LARS2 can contribute to the progression of COAD by controlling leucine metabolism and tumor growth and influencing resistance to immunotherapy." (PMID 40230854, 2025). "Genes and proteins regulating the TCA cycle (PDHA1, SUCLG2, SUCLG1, and IDH2) as well as mitochondrial function (VDAC1, MRPS31, LARS2, OPA1, and MTIF2) showed higher transcripts and protein levels in Wnt‐high compared with Wnt‐low tumor entities." (PMID 35904277, 2022). "Remarkably, specific aaRS genes do show a DNA profile reminiscent of an oncogene (e.g., GARS1, AIMP2, and YARS2) or tumor suppressor (e.g., NARS1, QARS1, LARS2, and RARS2)." (PMID 33266490, 2020). "These molecular alterations suggest that LARS2 and SEZ6L2 might contribute to COAD progression by promoting tumor growth and immune evasion, whereas SOX7 downregulation may facilitate tumor development by impairing tumor suppressive pathways." (PMID 40230854, 2025). "While LARS2 and SEZ6L2 may contribute to immune suppression and tumor immune evasion, SOX7 appears to promote CD8+ T cell infiltration and antitumor immunity." (PMID 40230854, 2025). "Although the precise control of immune infiltration by LARS2, SEZ6L2, and SOX7 in CD8+ T cells and tumor fibrotic process are not yet understood, the results are promising and justify additional research." (PMID 40230854, 2025).
cancer (4 papers, 2022 to 2025). A tumor composed of atypical neoplastic, often pleomorphic cells that invade other tissues. "The role of LARS2 in cancer indicates that aberrant expression of LARS2 might cause the occurrence of POI via inducing granulosa cell apoptosis." (PMID 35585880, 2022). "It has been reported that LARS2 is involved in the regulation of cell proliferation and apoptosis in cancer cell." (PMID 35585880, 2022). "The aberrant expression of LARS2 in cancer cells has been demonstrated." (PMID 35585880, 2022).
infection (1 paper, 2014). The state of being infected such as from the introduction of a foreign agent such as serum, vaccine, antigenic substance or organism. "The LARS2 pyrosequencing assay revealed similar DNA methylation differences between the three experimental conditions at all 3 additional CpG sites assessed in this amplicon, indicating a broad dynamic epigenetic change in this region in host cells upon infection with L. donovani." (PMID 25299267, 2014).
LARS2 also shares sentences with these, for which no sentence is quoted: premature ovarian failure (7 papers); ovarian dysfunction (6); hydrops (5); deafness (3); epilepsy (2); schizophrenia (2); testicular germ cell tumor (2); acute myelocytic leukemia (1); Alzheimer disease (1); breast carcinoma (1); Charcot-Marie-Tooth disease (1); cognitive decline (1); developmental delay (1); gastric cancer (1); hearing (1); Hearing impairment (1); Hyperglycemia (1); Hyperinsulinemia (1); Leigh syndrome (1); Leukoencephalopathy (1); mitochondrial disease (1); myocardial hypertrophy (1); myopathy (1); Neu-Laxova syndrome (1); osteoporosis (1); otospondylomegaepiphyseal dysplasia (1); Pearson marrow-pancreas syndrome (1); pontocerebellar hypoplasia (1); respiratory infection (1); Sensorineural hearing impairment (1).
A further 4 diseases each share a sentence with LARS2 in 1 paper.